CCR7 (C-C motif chemokine receptor 7)
Diseases named in the same sentence as CCR7 in open-access papers (continued):
Sharing a sentence is not in itself a finding about the gene and the disease.
tumor (continued). "Furthermore, a previous study identified a similar CCR7+ DC cluster and termed these as ‘mregDCs’ that can limit anti-tumour immunity." (PMID 39843887, 2025). "The immunomodulatory functions of DCs extend to their secretion of CCL8, which activates Src kinase signaling to potentiate CCR7-mediated T cell migration to the paracortical region, thereby promoting immune cell aggregation and activation while suppressing tumor progression." (PMID 41281945, 2025). "Moreover, both CCL21 and tumor-triggered pDC activation can be blocked by either CCL21 or CCR7 antibody neutralization." (PMID 39456552, 2024). "CCR7 and its ligands are crucially important for DC migration into lymph nodes from the tumor." (PMID 39684473, 2024). "Taken together with the increase in CCR7-positive T cells in tumor tissues, the induction of SCM phenotypes could be one of the potential mechanisms of the enhanced antitumor efficacy of 7 × 19 CAR-T." (PMID 39240078, 2024). "Moreover, research has suggested that CCR7 is a cell membrane receptor that mediates T- and B-cell migration and participates in the tumour immune response." (PMID 38762550, 2024). "Hence, we propose that Ccr7_DC.2 and Ccr7_DC.3 are terminal, tumour-residing CCR7+ DC states, and DCs that have transitioned beyond the intermediate Ccr7_DC.1 state become increasingly unlikely to egress." (PMID 38267413, 2024). "CCR7 belongs to the anti-tumor chemokine family, guiding dendritic cells (DCs) to migrate to lymphoid organs to initiate immune responses, activate the effector function of T cells, and exhibit anti-tumor activity." (PMID 38765682, 2024). "Tumours cultured ex vivo with IFNγ resulted in similar activation of CCR7+ DCs." (PMID 38267413, 2024). "The possible reason for this outcome could be attributed to the fact that CCR7 stimulates T- and B-cell infiltration at the tumour site, thereby leading to the killing of the tumour." (PMID 38762550, 2024). "Moreover, there is an upregulation of CC-chemokine receptor 7 (CCR7) to improve DC homing to tumor-draining lymph nodes or to tertiary lymphoid structures via lymphatic vessels or blood circulation, where they encounter and activate T cells." (PMID 38927447, 2024). "However, in Ccr7-/-mice, M057 and anti-VEGFR showed a comparable ability to inhibit lung tumor growth, supporting that increased tumor infiltration of CCR7+ DCs contributes to the enhanced anti-lung tumor effects of M057." (PMID 38250037, 2024). "In addition, CCR7 is also involved in tumor cell invasion, metastasis, development and epithelial mesenchymal transition, as well as in lymph node metastasis, invasion and migration." (PMID 38438469, 2024). "Next, we sought to address whether intra-tumour CCR7+ DCs, and their precise phenotype, influences clinical response to ICB." (PMID 38267413, 2024). "Importantly, we identified several lymphocyte activation ligands that were significantly upregulated on Ccr7_DC.2 versus other tumour CCR7+ DC states and Kaede-red dLN CCR7+ DCs, such as Il12b, Tnfsf4, Tnfsf9, Cd70 and Pvr." (PMID 38267413, 2024). "The concept that prolonged residence within tumours might influence CCR7+ DC fate and function is worthy of consideration given the known effects of the tumour microenvironment (TME) on other immune cell populations." (PMID 38267413, 2024). "Moreover, CD80 and CD86 expression was upregulated on Kaede-red versus Kaede-green tumour CCR7+ DCs, with expression levels on tumour Kaede-green CCR7+ DCs similar to migrated CCR7+ DCs in matched dLNs." (PMID 38267413, 2024). "Similarly, CCR7-CAR macrophages target lipid droplet-rich CCR7+ immunosuppressive cells within the tumor, with the potential to remodel the immunosuppressive TME." (PMID 38665921, 2024).
tumor (continued). "Here, we use a photo-tracking mouse model, combined with single-cell RNA sequencing (scRNA-seq), confocal imaging and spatial transcriptomics in mouse and human tissue samples, to interrogate the spatio-temporal dynamics of CCR7+ DCs, their roles within the tumour, and the effects of ICB." (PMID 38267413, 2024). "These molecules were also preferentially expressed on tumour-residing CCR7+ DCs in B16-F10 tumours." (PMID 38267413, 2024). "However, given our demonstration that many CCR7+ DCs acquire prolonged tumour residence, we sought to definitively track tumour DC egress to dLNs." (PMID 38267413, 2024). "Tumor cells expressing CCR7 could interact with CCL21 produced by lymphatic endothelial cells, resulting in lymphatic metastasis of tumor cells." (PMID 39175095, 2024). "However, relatively less information is known about mechanisms used by CCR7 on tumor infiltrating immune cells that would impact the TME and contribute towards tumor progression." (PMID 38539232, 2024). "CCR7 also facilitates the migration of DCs from the tumor microenvironment to the tumor-dLN." (PMID 38628676, 2024). "Given that a substantial proportion of CCR7+ DCs in the tumour failed to migrate to dLN, and that tumour CCR7+ DCs may associate with outcomes, we sought to identify which immune cells CCR7+ DCs may communicate with in the tumour." (PMID 38267413, 2024). "Thus, the precise temporal dynamic behaviour of CCR7+ DCs, the extent to which they act within the tumour versus dLN, and how these dynamics and site-specific cellular interactions are influenced by ICB remain to be clarified." (PMID 38267413, 2024). "Specifically, tumour-retained CCR7+ DCs may regulate the activation and expansion of anti-tumour cytotoxic T cells, but they could also be important targets of cancer immunotherapy." (PMID 38267413, 2024). "However, CCR7 is a cell membrane receptor that mediates T- and B-cell migration and is involved in the tumour immune response." (PMID 38762550, 2024). "Using fluorescence tracking of dendritic cells in the tumor using the Kaede photoconvertible mice, we have shown that following radiation therapy exposure to endogenous innate adjuvants DC migrate to the TdLN via a CCR7-dependent mechanism." (PMID 39622844, 2024). "We next asked whether the three transcriptionally distinct tumour CCR7+ DC states contributed equally to the dLN emigrants." (PMID 38267413, 2024). "In addition, the expression levels of CCR7 and integrin αvβ3 are positively correlated with the tumor size, clinical stage and lymph node metastasis of OSCC, and cell adhesion and migration are promoted by inducing integrin αvβ3 phosphorylation." (PMID 38539232, 2024). "However, the CCR7 expression scores in the cytoplasm, tumour size, age, CD8 and PDL-1 did not exhibit significant associations with patient prognosis." (PMID 38762550, 2024). "Similarly, overexpression of CXCR4 or CCR7 in NK cells improved migration and infiltration into specific tissues, reducing tumor burden and extending survival in mice." (PMID 38474415, 2024). "Recent studies also report that CCR7+ DCs may engage other immune cells in tumours, including CXCL13+ CD4+ T cells, regulatory T cells and NK cells, and may reside in TLS12,15." (PMID 38267413, 2024). "For example, immune checkpoint therapy increases interferon gamma (IFNγ) production by PD-1+CD8+ T cells that co-localise with CCR7+ DCs in tumours, which may activate tumour DCs32." (PMID 38267413, 2024). "Therefore, successful LN emigrants resemble newly-formed CCR7+ DC, and tumour-retained CCR7+ DCs acquire a distinct phenotype with prolonged tumour dwell-time." (PMID 38267413, 2024). "The abilities of cell migration and invasion were increased significantly when PCI-4B and PCI-37B cells were co-cultured with M2 macrophages; however, when we pretreated M2 macrophages with CCR7 mAb, the migration and invasion abilities of tumor cells (PCI-4B, PCI-37B) were significantly decreased." (PMID 38539232, 2024).
tumor (continued). "Next, knowledge of CCR7+ DC ontogeny remains incomplete, particularly the relative contribution of cDC subsets or monocytes to heterogeneous tumour-residing CCR7+ DC states, which may influence their ability to support CD8+ versus CD4+ T cell responses." (PMID 38267413, 2024). "Accordingly, we evaluated the density of CCR7-expressing CD11c+ MHC-II+ cells in the tumor." (PMID 38523774, 2024). "Within the TME, cDCs have been shown to acquire a common gene program characterized by the expression of immunoregulatory genes (e.g., CD274/PD-L1, PDCD1LG2/PD-L2 and CD200), LAMP3 and CCR7, thus informing the naming of these tumor-specific cells mregDCs or LAMP3+CCR7+ cDCs." (PMID 36949244, 2023). "Therefore, CCR7 overexpression in the tumor microenvironment is critical for cancer progression and metastasis." (PMID 36980764, 2023). "In addition, it has been reported that overexpression of CCR7 in HNSCC tissues facilitated the RhoA/ROCK pathway-mediated migration of tumor cells in HNSCC." (PMID 37600570, 2023). "Cord blood T-cells expressed enhanced levels of the tumor-homing receptor CCR7." (PMID 37780051, 2023). "A metastatic mechanism was demonstrated in which CCR7-expressing tumor cells could ‘home’ to lymph-nodes like immune cells." (PMID 37314567, 2023). "Additionally, responding patients had a lower tumor burden and displayed the expression of chemokine receptors (CCR7, CCR6, CXCR4, CXCR3, and CXCR5) on CD4+ T cells." (PMID 37174069, 2023). "Cord blood CD8+ T-cells are endowed with enhanced tumor-homing capabilities due to high levels of CCR7 expression, which in conjunction with greater proliferation may contribute to the superior GVL effect." (PMID 37780051, 2023). "The observed increase in the CCL19 expression may promote IFN‐γ‐dependent anti‐tumor defense by inducing the homing of CCR7+ T cells and DCs." (PMID 37675835, 2023). "LAMP3+DC highly expresses chemokine CCL19 and its receptor CCR7, which may recruit other immune cells to migrate to tumor tissues through the CCL19-CCR7 axis." (PMID 37675100, 2023). "During this cycle, CD103+/CD141+ DCs bearing CCR7 play a key role in delivering tumor antigens to TDLNs; furthermore, the paucity of CCR7 can lead to blocked T-cell initiation with tumor growth, and the loss of activated CD103+ DCs in tumors will reduce the efficacy of checkpoint blockade." (PMID 37482608, 2023). "Besides immune response, CCR7 signaling also contributes to tumor progression, especially metastasis to the lymph nodes." (PMID 38008741, 2023). "Anti-CCR7 CAR-Ms bearing the MerTK activation domain exhibited the highest tumor cell toxicity." (PMID 37147740, 2023). "However, we observe that initial CCR7-mediated localization of CD8 T cells to tumor draining lymph nodes is required to subsequently generate CD103+ CD8 T cells in tumors." (PMID 37072485, 2023). "As the results shown, CCR7 RNA expression level in TCGA was overexpressed in tumor samples." (PMID 37950222, 2023). "In B16-OVA expressing tumours, the administration of blocking antibodies targeted against L-selectin (which recognizes sulfated sialomucins displayed on HEVs) or anti-CCR7 (activates LFA-1 leading to lymphocyte arrest) prevented lymphocyte infiltration into tumours." (PMID 37287625, 2023). "In addition, lymphatic vessels express large amounts of CCL21, which provides migration guidance for tumor cells expressing the CCL21 receptor CCR7 and drives tumor cells to migrate into the lymphatic system." (PMID 36831512, 2023). "Moreover, pathways enriched in CCR7 + and IL7R + CD8 + T cell subgroups were associated with tumor proliferation and progression, tumor metastasis, and immunosuppression." (PMID 37221625, 2023). "Here, we selected CCR4 and CCR7, which showed the highest ratio of draining to contralateral lymph node enrichment and a particularly high specific enrichment into draining lymph node over the tumor." (PMID 37301772, 2023).
tumor (continued). "Identification of CCR7 expression in SUM149 cells prompts the hypothesis that tumor cells use this well-defined immune mechanism for lymphatic homing for LVSI." (PMID 37801190, 2023). "CyTOF comparison of CD8+ T cells within blood and tumor identified expansion of effector cells within TIL with an associated decrease in naïve (CD45RA+CCR7+) and terminally differentiated effector memory (TEMRA; CD45RA+CCR7–) populations." (PMID 36689623, 2023). "Thus, although the impact of the CCL21/CCR7 signaling on anti-tumor immunity remains controversial, the fact that CCL21 expression can induce an immune response provides a rationale for the use of CCL21 in cancer immunotherapy." (PMID 37664721, 2023). "Moreover, CCR7-bAbs suppressed tumor cell proliferation, alone, and even more when combined with TMZ." (PMID 37314567, 2023). "In HNSCC, hypoxia may promote pDC migration to tumor-draining lymph nodes and lymphatic metastasis by upregulating CCR7 expression." (PMID 37817484, 2023). "Additionally, R848 induced expression of co-stimulatory molecules and chemokine receptor CCR7, which is involved in pDC recruitment to the tumor site." (PMID 38239354, 2023). "However, it’s important to note that CCR7 plays a dual role in cancer, sometimes promoting tumor progression and, at other times, bolstering antitumor immunity." (PMID 37944262, 2023). "The results revealed that CCR7 was notably up-regulated in various tumor types, including HNSCC." (PMID 35904690, 2022). "VEGF-C mediated potentiation of adoptive T-cell therapy was dependent on CCR7-mediated attraction of naïve T cells to the local TME; this was shown to occur through VEGF-C-induced CCL21 upregulation in tumor lymphatics because CCR7 blockade reversed the potentiating effects of VEGF-C." (PMID 35216243, 2022). "In the case of solid tumors, since memory CAR-T cells express CCR7, they may tend to home to lymph nodes but fail to infiltrate into the tumor tissue in vivo." (PMID 35990619, 2022). "Our data demonstrated that GPX8 was correlated with mRNA expression of immune markers of CD8+ T cells (CD8B), CD4+ T cells (CD4), T cells (CD3D), macrophages (CD68 and ARG1), neutrophils (ITGAM and CCR7), dendritic cells (NRP1), NK cells (B3GAT1), and tumor-associated fibroblasts (FAP)." (PMID 36061208, 2022). "Since PD-1, ZAP-70, CD28 and CCR7 are all normally expressed in immune cells, the co-expression of these markers may reflect a tumor environment that promotes anti-tumor immunity." (PMID 35203305, 2022). "Besides, JBH492 is an antibody–drug conjugate that consists of an antibody against CCR7 on tumor cells combined with the steroid DM4, which leads to inhibition of tumor cell proliferation." (PMID 35702353, 2022). "Alternatively, ET-1-induced vasoconstriction could trap CCR7-expressing dendritic cells or macrophages that traffic the tumor cells to the lymph nodes via the vasculature." (PMID 35203305, 2022). "CCR7 is a lymphocyte-specific G protein-coupled receptor that executes a unique antagonistic role in tumorigenesis by transferring tumor cells to the T cell region of lymph nodes." (PMID 36425071, 2022). "Efficient CCR7-directed migration could play an important role in optimizing anti-tumor T cell responses in vivo due to the increased lymph node homing of DC vaccine." (PMID 35269457, 2022). "Armoured CAR T cells expressing CCL19, a ligand for CCR7 which attracts both T and DC cells, alongside IL-7, was able to increase DC and T cell infiltration and colocalisation in tumours, achieving complete regression in some murine models and significant growth repression in others." (PMID 35205725, 2022). "For solid tumors, CCR7 induced EMT enhanced tumor cell migration and invasive behavior." (PMID 35203305, 2022).
tumor (continued). "Based on this, research also deemed that PGE2 can upregulate CCR7 at least partly, via inhibiting the activation of LXRα in monocyte-derived DCs (moDCs), so as to promote the infiltration of DCs in the tumor site and avoid tumor immune escape." (PMID 35281921, 2022). "Moreover, tumour tissues exhibited enhanced expression of CCR7 after PTX treatment, which was similar to that observed in B16F10 treated with PTX in vitro." (PMID 35280672, 2022). "Therefore, targeting the CCL19/CCL21/CCR7 axis to inhibit lymphatic metastasis but maintaining a robust antitumor immune response has increasingly become a bright spot in tumor immunotherapy." (PMID 35702353, 2022). "According to a previous report, several compounds with CCR7-binding ability were screened from more than 2 million combinations by analysing the structure of human CCR7; these compounds have the application potential as CCR7 antagonists to prevent tumour metastasis." (PMID 35280672, 2022). "DC migration to the tumour driven by the chemokine receptor CCR7 could be improved by use of armoured CAR T cells." (PMID 35205725, 2022). "Many COX-2 inhibitors have been investigated for their anti-tumor effects, and may reduce the numbers of CCR7-directed metastases to the lymph nodes." (PMID 35203305, 2022). "Downregulation of CCR7 in animal models limited tumor aggression." (PMID 35203305, 2022). "Moreover, the expression of CCR7 in tumour tissues of mice treated with PTX (2.5 mg/kg) was increased by 1.3-fold compared with the vehicle control group." (PMID 35280672, 2022). "The chemokine receptor CCR7 has been proven to guide T‐cell chemotactic homing to tumor tissues." (PMID 35474948, 2022). "Next, we investigated the latent role CCR7 plays in the tumor immunology of HNSCC." (PMID 35904690, 2022). "These regulatory features may include metabolic features of the tumor—for instance, it has been reported that oxidized cholesterol ligands secreted from tumors can suppress the expression of CCR7 in DCs-, and this impairs the migration from the tumor to TdLN." (PMID 35487695, 2022). "CCL21/CCR7 has been gradually recognised as a potential therapeutic target in many tumours." (PMID 35280672, 2022). "Thus, the presence of the Zbtb46dtr bone marrow ensured that cDCs that can express CCR7 are present during animal and tumor development to ensure normal immune biology." (PMID 35487695, 2022). "Furthermore, it has recently been shown that expression of immunosuppressive CD73 and CCR7 was lower on peripheral T cells in healthy volunteers as well as in tumor patients with increasing age." (PMID 35625386, 2022). "For instances, CCL19 could suppress tumor angiogenesis by promoting miR-206 expression dependently on CCR7, and thereby inhibiting the Met/ERK/Elk-1/HIF-1α/VEGF-A pathway." (PMID 35770088, 2022). "This could be due to the presence of CCR7-expressing immune cells in the tumor, cells which normally express ET-1, in the presence of the ET-1-mediated vasoconstriction." (PMID 35203305, 2022). "Also, higher expression levels of CCR7 mRNA were observed in tumor tissue compared to the control tissue (median RQ: 11.268 and 8.747, respectively), but this difference was not statistically significant (p > 0.05, Mann-Whitney U-test)." (PMID 35160116, 2022). "Activation of CCL21/CCR7 promoted proliferation and migration of tumour cells." (PMID 35280672, 2022). "This phenotype could correspond to antigen presenting cells-like hybrid tumour associated neutrophils (APC-like TAN) in which markers for both granulocytes (CD11b, CD66b, CD15) and monocytes (CD33, CD14, HLA-DR, CCR7, CD86, CD20) co-exist." (PMID 36189320, 2022). "Also, since CCL21–CCR7 axis mediates tumor metastasis, blocking CCR7 in cancer cell or inhibition CCL21 secretion can test for restrict metastasis." (PMID 34671596, 2021).